AR (androgen receptor)
Diseases named in the same sentence as AR in open-access papers (continued):
Sharing a sentence is not in itself a finding about the gene and the disease.
tumor (continued). "Specifically, androgen receptor overexpression has been linked to enhanced tumor growth and invasive potential in GB." (PMID 40722784, 2025). "Emerging radiotracers targeting the GRPR, AR, and amino acid transporters offer a multifaceted diagnostic framework that reflects the tumor heterogeneity and evolutionary dynamics inherent in PCa." (PMID 41226028, 2025). "This splice variant has been detected in circulating tumor cells (CTCs) and is associated with resistance to androgen receptor axis-targeted agents (ARATs) such as enzalutamide and abiraterone." (PMID 40034825, 2025). "A notable clinically validated example is the androgen receptor splice variant 7 (AR-V7), frequently detected in circulating tumor cells and peripheral whole blood of patients with metastatic castration-resistant prostate cancer (mCRPC)." (PMID 40430531, 2025). "The speckle type BTB/POZ protein gene (SPOP) is a frequently mutated gene in PCa that serves as a crucial tumor suppressor by functioning as a ubiquitin ligase, mediating the intracellular degradation of AR." (PMID 41247636, 2025). "Spatial profiling demonstrates that TREM2 or SPP1-labeled, AR-imprinted macrophages cluster near tumor nests, cancer-associated fibroblasts (CAFs), and vascular hubs." (PMID 41488638, 2025). "Amplification of the AR has been identified in up to 20% of mCRPC patients and is associated with response to the low levels of circulating and/or intra-tumor androgens." (PMID 40510029, 2025). "Progesterone has been shown to inhibit tumor growth via the PR, while AR expression has been associated with the response to EGFR-TKI therapy." (PMID 40868244, 2025). "Tumor grade, however, was significantly associated with AR expression and persisted as significant after Bonferroni correction." (PMID 40734715, 2025). "The biological mechanisms underlying the association of AR and aggressive tumor features remain to be elucidated." (PMID 41463239, 2025). "Since AR copy number gain is correlated with higher cell-free DNA levels which are often associated with higher tumor volume, liquid biopsy can create a confounding effect for the prognostic value of AR amplifications." (PMID 38383885, 2025). "In these studies, AR expression was found to be associated not only with tumor progression but also with tumor classification, highlighting its potential utility as a diagnostic tool." (PMID 40286049, 2025). "Of note, the repression of WT1 and FOXA1, elicited by the signature, caused a downregulation of the Androgen Receptor (AR) expression, an impairment of tumor-spheroid formation and reversed cancer cell stemness." (PMID 40399259, 2025). "The F877L mutation alters the conformation of AR when binding with drugs, activating downstream signaling pathways and helping the tumor evade anti-androgen therapy." (PMID 40008000, 2025). "Patient WA_39 illustrates the divergent pathways to castration resistance, with two of three tumor sites harboring AR amplification but a third site manifesting a hotspot mutation." (PMID 40824681, 2025). "ADT causes tumor regression by inducing the apoptosis of the tumor epithelial luminal and stromal cells that express AR." (PMID 40141159, 2025). "Previous studies have reported associations between AR/ER ≥ 2.0 with poorer clinical features like positive lymph nodes, larger tumor sizes, higher histological grades and overexpression/amplification of the HER2 gene in ER+ BC patient." (PMID 40593140, 2025). "In the context of prostate cancer, circRNAs have been implicated in modulating androgen receptor signaling, regulating oncogenes and tumor suppressors, and reshaping the tumor microenvironment." (PMID 41561631, 2025). "Androgen deprivation therapies (ADTs) induce only temporary disease remission and, in all treated patients, the tumor relapses by further acquiring mutations in AR pathway genes that restore its activity." (PMID 40570057, 2025).
tumor (continued). "The results showed that the genetic alterations of the AR in HNSCC tumor samples include copy number deletions, point mutations, and copy number amplifications, with copy number deletions and point mutations accounting for the majority." (PMID 40729027, 2025). "Taxane anticancer drugs cause cell‐cycle arrest at the G2/M phase, while the AR is a critical regulator of G1 to S phase transition for androgen‐dependent tumor cell proliferation." (PMID 39651632, 2025). "In PCa, these factors activate STAT3, NF-κB, and androgen receptor splice variant 7 (AR-V7) signaling, thereby promoting tumor-cell survival, immune evasion, and androgen desensitization, and markedly increasing proliferation." (PMID 41514658, 2025). "To further investigate the relationship between NO, ER stress, and tumor burden, we utilized an additional model representing complete AR loss, a hallmark of aggressive PCa progression." (PMID 41198652, 2025). "The DNA demethylase TET2 was shown to interact with AR to regulate the expression of tumor-suppressor genes, suggesting that it has a role in tumor suppression and its loss can lead to the progression of PCa." (PMID 40833121, 2025). "Androgen blockade or AR loss increases CCL2 production from both tumor cells and stromal compartments, enhancing CCR2+ monocyte influx and downstream STAT signaling, which subsequently accelerates tumor progression and dissemination." (PMID 41488638, 2025). "In ER-positive cases, AR expression was linked to smaller tumor sizes, lower Nottingham grades, and less frequent tumor necrosis." (PMID 40734715, 2025). "Similar to T877A, the H874Y mutation enables AR to function under androgen-deficient conditions, facilitating tumor resistance to treatment." (PMID 40008000, 2025). "HOXB13 germline variants were also shown to have an AR-independent role in PCa progression, through lipid accumulation that promotes cell motility and tumor metastasis." (PMID 40833121, 2025). "Within pT2–pT4 tumors, AR positivity was associated with advanced tumor stage (p = 0.0014), nodal metastasis (p = 0.0060), and AR positivity was significantly linked to reduced overall survival (p = 0.0210) with a HR = 1.48 (95%CI 1.06–2.05)." (PMID 41463239, 2025). "The resistance of CRPC is primarily associated with AR mutations, activation of downstream signaling pathways, and metabolic reprogramming, enabling tumor cells to survive in a low-androgen environment." (PMID 40008000, 2025). "AR is a major regulator of lipid metabolic genes involved in lipid synthesis, uptake, and storage, and in CRPC, reactivation of AR-induced lipid biosynthesis has been linked to tumor growth and metastasis." (PMID 41277556, 2025). "Conversely, mutations in the AR gene, which similarly tend to arise later in the tumor’s lifespan, were truncal in fewer than 20% of cases." (PMID 40824681, 2025). "This suggests that AR mutations predominantly occur following tumor spread, consistent with previous reports." (PMID 40824681, 2025). "The transition from CRPC to NEPC is associated with the gradual failure of the AR signaling pathway, leading to the acquisition of new biological characteristics and aggressiveness of tumor cells." (PMID 39816691, 2025). "Cell-free DNA (cfDNA) sequencing is the most widely used clinical liquid biopsy platform and has identified circulating tumor DNA content and AR genomic alterations as biomarkers that associate with ARPI resistance and poor survival." (PMID 39912912, 2025). "Our case underscores the importance of considering molecular signatures, particularly those related to the HER2 and AR pathways, early in the diagnostic process for this rare tumor type." (PMID 39814370, 2025). "AR reactivation is triggered by AR gene amplification, AR point mutations, and tumor-intracrine androgen synthesis." (PMID 40087774, 2025). "Alterations in AR signaling are closely linked to metabolic reprogramming that supports tumor growth and disease progression." (PMID 40647540, 2025).
tumor (continued). "Immunohistochemistry performed as part of the diagnostic work up on the nodal tumour showed positive staining for androgen receptor (AR), NKX3.1, PSA polyclonal, and Synaptophysin." (PMID 38374116, 2024). "Available evidence has shown that AR is a tumor suppressor and that its expression is associated with improved prognosis in ER+ BC." (PMID 39650747, 2024). "AR is overexpressed in colon tumor tissue and is associated with tumor size, differentiation, and distant metastasis." (PMID 38867310, 2024). "In CRPC cells, these overexpressed lncRNAs can interact with both C-terminal truncated (AR-V7) and full-length AR, causing ligand-independent activation of the AR-regulated transcriptional program and tumor cell proliferation." (PMID 38275816, 2024). "Specifically, androgen receptor (AR) signaling has been linked to the suppression of CD8+ T cell function within the tumor microenvironment." (PMID 39286780, 2024). "This study aims to elucidate the role of DHT in modulating tumor cell susceptibility to immune-mediated cytotoxicity, particularly through the AR and NF-κB pathways, and to explore the potential implications for cancer treatment in EBVaGC." (PMID 39335190, 2024). "While age is a major risk factor for this disease, the expression of AR is a key factor for tumor proliferation, not only in androgen-sensitive but also in castration resistant PCa cells." (PMID 39668349, 2024). "Meanwhile, Vav3 is a signal molecule in proteoglycans in cancer that is considered an important tumor‐associated pathway and AR is enriched in oocyte meiosis, a pathway related to cell division." (PMID 38804848, 2024). "FT-6876 is a bromodomain inhibitor that causes a decrease in AR target gene expression, which is consistent with tumor growth inhibition." (PMID 38104650, 2024). "During CRPC development, the tumor undergoes several adaptions counteracting supraphysiological androgen levels, including increased androgen synthesis, AR amplification, AR mutation, AR alternative splicing, MYC overexpression, and hyperactive STAT signaling." (PMID 39199642, 2024). "Early steps in cancer development and progression are closely linked to fibroblast senescence and transformation into tumor-promoting cancer-associated fibroblasts (CAFs), suppressed by the androgen receptor (AR)." (PMID 38310103, 2024). "Recent analyses of cell‐free circulating tumor DNA (ctDNA) from patients with mCRPC have shown that AR amplification is associated with resistance to second‐generation ARSIs." (PMID 38600681, 2024). "The exact mechanisms and pathways underlying the tumor-suppressive activity of AR leading to growth suppression and cellular senescence are not fully understood." (PMID 39676172, 2024). "Co-culture of AR-deficient prostatic stromal cells with PCa epithelial cells also appeared to enhance tumor cell growth in both in vitro and xenograft models." (PMID 39369165, 2024). "Molecular tumour profiling and the identification of targetable mutations are a prime focus for PM PCa research, and there are, for example, several androgen receptor pathway inhibitors available that have traditionally been mainstays of treatment." (PMID 38633827, 2024). "Low AR staining was significantly associated with adverse histopathological and clinical features in several tumor types." (PMID 38790919, 2024). "The correlation analyses indicate that AR signaling in tumor is associated with reduced LYL1 expression in PCa." (PMID 39668349, 2024). "This gene fusion upregulates ERG expression and reactivates AR signaling in tumor cells, with amplifications and/or mutations of AR strongly correlating with the onset of mPCa." (PMID 39770431, 2024).
tumor (continued). "Specifically, the activation of the MAPK pathway by AhR can lead to increased AR signaling, while cross-talk with the Wnt pathway can influence gene expression profiles associated with tumor growth and metastasis." (PMID 39184676, 2024). "Consecutive liver sections further confirmed that AR WT induce tumor in NRAS dependent HDT mice, and the AR mutations further accelerated hepatocarcinogenesis as indicated by KI67 staining." (PMID 38182647, 2024). "We provide compelling evidence that Cdk12 is a tumor suppressor gene and demonstrate its loss promotes androgen receptor (AR) and MYC-mediated hypertranscription, transcription-replication conflicts (TRCs), and resultant DNA damage." (PMID 39368479, 2024). "PTEN, which leads to the downstream activation of the PI3K/Akt and AR signaling pathways, plays a crucial role in tumor suppression, and its loss is associated with poorer clinical outcomes in patients with mCRPC." (PMID 38339274, 2024). "The creation and testing of new DSRCT PDX models, better reflecting DSRCT tumor biology including tumor-associated stromal cells, will be critical in further exploring the AR-independence we observe in DSRCT cell lines." (PMID 38575753, 2024). "The tumor is characterized by diffuse infiltrative discohesive ovoid/round eosinophilic cells with pleomorphic nuclei that immunophenotypically express AR and GCDFP, and exhibit loss of/or abnormal E-cadherin expression." (PMID 37886914, 2023). "The expression level of ER and AR proteins was associated with decreased tumor-infiltrating immune cells and decreased PD-L1 expression." (PMID 36721218, 2023). "The overall conclusion of this study is that tumor AR protein levels are associated with better OS in female patients, and not in male patients." (PMID 36833272, 2023). "For instance, FOXA1, NWD1 and MAZ have been shown to promote tumor progression by modulation of androgen receptor expression and are frequently linked with poor prognosis." (PMID 36818049, 2023). "Among AR-association gained genes, new candidate genes that strongly associated with aggressive tumor traits were sprouty related EVH1 domain containing 3 (SPRED3), transmembrane serine protease 11F (TMPRSS11F) and solute carrier family 1 member 1 (SLC1A1)." (PMID 36809527, 2023). "In TNBC subsets, AR positivity is associated with improved features, such as lower tumour grade, risk of nodal involvement and lower proliferative index." (PMID 36831687, 2023). "Androgen receptor (AR) is a ligand-activated transcription factor controlling a variety of cellular events implicated in tumour progression and AR signalling is central to PCa." (PMID 37160910, 2023). "ARIs therefore, reduce the activity of AR signalling often through the inhibition of its nuclear translocation and chromatin binding of the AR leading to the inhibition of AR target gene expression, subsequently causing the suppression of tumour growth." (PMID 36937454, 2023). "Under Enz treatment, however, tumor-suppressive miR-644a negatively regulates multiple oncogenes encoding AR regulators (such as c-Myc, BCL-XL, and BCL-2)." (PMID 37370750, 2023). "In localized disease, androgen receptor activity was protective whilst interferon signaling (that strongly associated with tumor lymphocyte infiltration) was detrimental." (PMID 36798177, 2023). "The reprogramming of the AR cistrome leading to increased plasticity, de-differentiation, and the reactivation of developmental programs is associated with tumor progression and poor outcomes." (PMID 36768610, 2023).
tumor (continued). "They showed that loss of CHD1 induces the transcription factors of GR, BRN2, TBX2, and NR2F1, which are required to promote tumor heterogeneity and resistance to AR inhibitors in CHD1-deficient tumors." (PMID 36776288, 2023). "Overall, this study demonstrates that in a subset of CRPC patients, tumor cells can accumulate very high numbers of structurally diverse AR gene copies under pressure of AR-targeted therapy, and implicates ecDNA as an underlying mechanism." (PMID 37636316, 2023). "For instance, in AR-null cell line models and patient tumor samples, DNA methylation has been implicated in regulating AR expression." (PMID 37455903, 2023). "In another report, an Arv7-mediated CRPC has been created utilizing an active AR splice variant to inhibit the tumor." (PMID 37740236, 2023). "NEPC is commonly characterized by the loss of AR signaling in the process of transdifferentiation, which enables tumor cells to escape AR pathway inhibition reducing responsiveness to hormonal therapies." (PMID 37065756, 2023). "AR mutation burden usually increases with tumor stage, and alterations oftentimes involve missense mutations in the LBD." (PMID 36937425, 2023). "CD8+ T cells have robust AR expression, and tumor-derived androgen causes a paracrine effect on T cells by inhibiting nuclear translocation of SREBF1." (PMID 37738978, 2023). "PSA expression is regulated by androgen receptor (AR), and it is normally synthesized in epithelial cells of the prostate gland with abnormally high levels implicated in tumor recurrence in men with PCa." (PMID 37561382, 2023). "This is associated with increased in vitro cell survival and with tumor progression, as the AR promotes the activation of DNA repair machinery genes." (PMID 37444473, 2023). "It results in tumour regression in castration-resistant xenograft models, and was reported to show persistent in vitro activity in the setting of AR splice variants such as AR-V7." (PMID 36609251, 2023). "Testosterone and its 5α-reduced metabolite, dihydrotestosterone (DHT), bind to the androgen receptor (AR), a ligand-dependent nuclear transcription factor, causing tumor growth and increased expression of prostate-specific antigen (PSA), among other functions." (PMID 38106489, 2023). "In this study, it is reported that AR signaling pathway is evidently activated in tumor‐associated macrophages (TAMs) of PCa both in mice and humans." (PMID 37092583, 2023). "An experiment in these cells has shown that knock-down of PRKAG2-AS1 and HOXC-AS1 leads to suppression of CRPC tumor growth in addition to inhibition of expression of AR and AR variant." (PMID 37025585, 2023). "Chemoprotection is down-regulation from 5-ARi and consequent reduction in binding sites associated with tumor translocation genes and improvement of DNA double stranded break induced by AR signaling." (PMID 37548746, 2023). "The type II ADI CWR-R1ca cells provide a good in vivo model to study tumor metastasis since cells of this line express AR, AR-splice variant-7 and PSA." (PMID 37103355, 2023). "Treatment of PLK1 inhibitor caused reduced AR protein level and inhibited tumor growth in LNCaP CRPC xenografts." (PMID 36098827, 2022). "Paradoxically, some other studies have shown the opposite trend where AR positivity has been associated with younger age at diagnosis, higher nuclear grade, higher tumor stage, greater lymph node metastases and increased mortality." (PMID 36139643, 2022). "Despite initial success of androgen-deprivation therapy, many men develop androgen-independent MCRPC, in which mutations or splice variants enable the tumor to continue to rely on androgen receptor signaling." (PMID 35109825, 2022). "LNCaP95 xenografts are androgen-independent tumours, expressing high levels of AR, AR splice variants (AR-Vs), and AR target genes such as PSA." (PMID 35832549, 2022).